TNF (tumor necrosis factor)
Diseases named in the same sentence as TNF in open-access papers (continued):
Sharing a sentence is not in itself a finding about the gene and the disease.
diabetic neuropathy (continued). "Another study indicates that inhibition of NF-κB inflammatory cascade using JSH-23 reversed the functional, sensorimotor and biochemical deficits by decreasing neuroinflammation (IL-6, TNF-α, COX-2 and iNOS) and improving antioxidant defence (Nrf2 and HO-1) in diabetic neuropathy." (PMID 34566656, 2021). "Palmatine inhibited the expression of P2X receptor in hippocampus, resulting in attenuation of diabetic neuropathy, which may be related to the inhibition of ERK1/2 phosphorylation and the release of tumor necrosis factor (TNF)-α and IL-1β in hippocampus." (PMID 31396083, 2019). "The action of TNF in the DRG is expected to produce a pro-nociceptive effect, and its overexpression in this sensorial organ is involved with pathological pain sensitization in models of neuropathic pain, acute herpetic neuralgia, and diabetes neuropathy." (PMID 32038637, 2019). "Emerging evidence indicates that cytokines including tumor necrosis factor alpha (TNF-α), interleukins (ILs), adhesion molecules, chemokines, and other soluble molecules may be involved in the pathogenesis of experimental diabetic neuropathy." (PMID 25961054, 2015). "Increased TLR4 messenger ribonucleic acid (mRNA) and TNF-α levels were observed in the spinal cords of rats with streptozocin (STZ)-induced DM and correlated positively with mechanical and thermal hypersensitivity, supporting their role in the development of diabetic neuropathy." (PMID 39408723, 2024). "Several biomarkers have been suggested, as neuron-specific enolase, toll-like receptor 4 or tumor necrosis factor alpha (TNF-α), but they are not specific of diabetic neuropathy." (PMID 32092076, 2020).
liver cirrhosis (72 papers, 2007 to 2025). "Methylobacterium has previously been identified as an opportunistic pathogen associated with increased levels of TNF-α and IL-1β in liver cirrhosis—a disorder characterized by dysbiosis, impaired intestinal function, and microbial translocation." (PMID 40871439, 2025). "TNF-α is the top upstream regulator in the pathogenesis of liver cirrhosis and contributes to loss of the LSEC phenotype." (PMID 38713515, 2024). "TNF-a is also induced in the Purkinje neurons of patients who die with liver cirrhosis and contributes to the loss of Purkinje cells in these patients." (PMID 32087723, 2020). "Our study confirmed that the GG genotype of the TNF-α −238 gene promoter is implicated in the probability of liver cirrhosis, supporting our previous data in a different and larger sample of HIV/HCV coinfected patients." (PMID 25013899, 2014). "The linear regression analysis demonstrates that the genotype GG at -238 TNF-α promotor gene was the independent factor associated to liver cirrhosis." (PMID 23840511, 2013). "In this cohort of Caucasian patients, we found that TNF-α -238 polymorphism was involved in the risk of liver cirrhosis." (PMID 23840511, 2013). "To validate the ability of the assay to capture and differentiate between subtly different EC morphologies, we validated our analysis pipeline using examples of ECs exposed to different concentrations of the liver cirrhosis associated proinflammatory stimuli TNF-α and LPS." (PMID 39129954, 2024). "Liver cirrhosis was associated with a −238 TNF-α polymorphism in these patients." (PMID 25013899, 2014). "It is stressed the importance of immunogenetic factors (TNF-α polymorphism at -238 position), above other factors previously accepted (age, gender, alcohol, immunodepression), on the evolution to liver cirrhosis among HIV-infected patients with established chronic HCV infections." (PMID 23840511, 2013). "In liver cirrhosis, Kupffer cells are activated and release multiple inflammatory mediators and chemokines, such as tumor necrosis factor (TNF-α), interleukin-6 (IL-6), and reactive oxygen species (ROS)." (PMID 39958826, 2025). "Certain inflammatory markers, including tumor necrosis factor and interleukins, which become elevated in liver cirrhosis, also play roles in stimulating certain areas of the brain, which can lead to fatigue." (PMID 39318930, 2024). "Ethanol per se and liver cirrhosis, as a pro-inflammatory condition, promote the production of IL-6 and TNF-α, increasing the synthesis of RANKL and, consequently, promoting bone resorption." (PMID 38472981, 2024). "CXCL1, IL-1β, and TNF-α were obviously increased in the liver cirrhosis group compared with the control group." (PMID 37273916, 2023). "Gene polymorphisms of IL-10, IL-18, TGF-β1 have been confirmed to be related to liver cirrhosis by our study, however, it is accepted that IL-1β, IL-28, especially TNF-α plays an important role in the occurrence and development of liver cirrhosis." (PMID 37101651, 2023). "The higher sCD137 of patients with HCV-related liver cirrhosis correlated with serum tumor necrosis factor levels." (PMID 38139346, 2023). "Inferior secretion of TNF-α by plasma cells compared with liver cirrhosis indicated diminished effector function of plasma cells in ACLF." (PMID 36505417, 2022). "We conclude that Klotho is increased in liver cirrhosis, being related to the TNF-α, lipid peroxidation, and especially to liver function impairment." (PMID 36009045, 2022). "The Purkinje neurons of patients who died with liver cirrhosis exhibited increased TNF-a content (p = 0.01) compared to that in control subjects who died without liver or neurodegenerative diseases." (PMID 32087723, 2020). "Liver cirrhosis is a known proinflammatory condition as represented by elevated levels of tumor necrosis factor-α (TNF-α), interleukin-1β (IL-1β), and IL-6." (PMID 32731496, 2020).
liver cirrhosis (continued). "It has been demonstrated that rats with liver cirrhosis have markedly higher serum TNF-α levels, which is in agreement with the present results." (PMID 31565053, 2019). "In patients with liver cirrhosis, elevated circulating levels of the proinflammatory cytokine TNF-α were recorded." (PMID 28744340, 2017). "The previous studies revealed that increased levels of TNF-α as well as IL-2, IL-6, and IL-10 in serum of patients play important roles in the progress of inflammation of severe hepatitis B-related liver cirrhosis." (PMID 27975051, 2016). "Other authors observed higher Il-6 and TNF-α concentrations in patients with liver cirrhosis compared with healthy volunteers." (PMID 26090463, 2015). "Patients with the GG genotype at position −238 in the proximal promoter of the TNF-α gene showed significantly higher values of liver stiffness and a higher proportion of liver cirrhosis than those with genotypes GA/AA." (PMID 25013899, 2014). "In this study, the altered intestinal epithelial barrier function in rats with liver cirrhosis was observed with an increase in TNF-α and IL-6 expression levels in small intestine." (PMID 25171482, 2014). "In cases of liver cirrhosis, the levels of tumor necrosis factor-alpha (TNF-α) also increase, which contributes to the accumulation of macrophages in the lumen of the pulmonary vessels." (PMID 23587191, 2013). "Single nucleotide polymorphism of TNF-α and IL-10 genes studied in patients with HIV-HCV coinfection with chronic hepatitis or liver cirrhosis." (PMID 23840511, 2013). "In cases of liver cirrhosis, the levels of tumor necrosis factor-alpha (TNF-a) also rise, and this contributes towards the accumulation of macrophages in the lumen of the pulmonary vessels." (PMID 20011928, 2009). "TNFα plays a crucial role in the pathogenesis of complications of liver cirrhosis." (PMID 41004464, 2025). "These novel drugs, as well as biologicals targeting the TNF-a signaling pathway may in the future find a role in slowing the progression to liver cirrhosis in BA and prolonging transplant free survival." (PMID 40607400, 2025). "In the coculture, TNF-α concentration in the supernatant was enriched compared to the control and the transwell condition independent of Trm inducing cytokines and also mimicking ex vivo changes in pediatric liver cirrhosis." (PMID 40607400, 2025). "Increased presence of proinflammatory TNF-α in liver cirrhosis is well documented." (PMID 40607400, 2025). "Furthermore, following stimulation with IL-12 + IL-18, the expression of IFNγ and TNFα was reduced in CD8+ T cells from compensated liver cirrhosis in comparison with healthy controls." (PMID 41028194, 2025). "Among CHB patients with liver cirrhosis, TNF is found to correlate with ongoing inflammation." (PMID 38114718, 2023). "In our study, we found that TNF-α, APTT, K, the diameter of the portal vein, and the history of splenectomy or embolization were related to PVT, which can help early identify the population in the liver cirrhosis with a high risk of PVT." (PMID 36717769, 2023). "Moreover, we next measured the levels of the inflammatory cytokines, including IL-6, CXCL1, IL-1β, and TNF-α, in the intestine to examine the role of liver cirrhosis on inflammatory response following vitamin D treatment." (PMID 37273916, 2023). "In liver cirrhosis, the distortion of the vascular architecture facilitates the escape of intestinal bacteria to the systemic circulation, stimulating many cells of the innate immune system that can secrete proinflammatory cytokines, such as the TNF-α." (PMID 36009045, 2022). "Liver cirrhosis was significantly associated with IL-6 and IL-8 over the median but not with the TNF-α values." (PMID 36009045, 2022).
liver cirrhosis (continued). "As the M1 phenotype is more frequently expressed, after activation, infiltrating hepatic macrophages can facilitate inflammation and liver cirrhosis by releasing pro-inflammatory interleukin 1β and TNF-α, and produce transforming growth factor-β and platelet-derived growth factor." (PMID 35665350, 2022). "TNF-a is also increased in the Purkinje neurons of patients who die with liver cirrhosis." (PMID 32087723, 2020). "The MDM2 mRNA levels of patients with HBV-related HCC were higher than those of patients with liver cirrhosis and chronic hepatitis B. The plasma levels of IL-6 and TNF-α were significantly higher in HBV-related HCC patients than that in liver cirrhosis and chronic hepatitis B patients." (PMID 33173438, 2020). "We also assessed whether TNF-a is induced in the Purkinje neurons of patients who die with liver cirrhosis and have suffered sustained hyperammonemia." (PMID 32087723, 2020). "Moreover, TNF-a expression is also increased in Purkinje neurons of patients who die with liver cirrhosis and are exposed to sustained hyperammonemia." (PMID 32087723, 2020). "Increased TNF-a expression may also contribute to the degeneration of Purkinje neurons in the cerebellum of patients who die with liver cirrhosis, as reported recently by our group." (PMID 32087723, 2020). "Additional experiments demonstrating the impact of IFNγ on TNFα and IL-6 production by CD14positive myeloid ascites suggested that NK cells might have indeed a regulatory role during peritonitis in patients with liver cirrhosis." (PMID 31440239, 2019). "In addition, activation of inflammatory cells in patients with liver cirrhosis promote the production of pro-inflammatory factors such as tumor necrosis factor (TNF) and interleukin (IL)-1, which can decrease bone mass." (PMID 29768330, 2018). "Elevated TNFα may also contribute to the development of circulatory dysfunction in liver cirrhosis." (PMID 41004464, 2025). "However, taking into account that most neurological alterations in patients with liver cirrhosis and HE are reversible after liver transplantation, it would be expected that treatment with anti-TNF-α could also restore most of these neurological alterations." (PMID 27623772, 2016). "Genes related to senescence (e.g., PTPRC, TIGIT, and TNF) and exhaustion (e.g., PDCD1, CTLA4, LAG3, and TNFRSF9) were highly enriched in CD4+ and CD8 + T cells from the participants with liver cirrhosis." (PMID 37735474, 2023). "Studies have proposed that tumor necrosis factor-alpha (TNF-α), produced by Kupffer cells and macrophages, plays a key role in the pathogenesis of liver cirrhosis." (PMID 37397479, 2023). "We found significantly higher expression of markers of T-cell senescence (e.g., PTPRC, TIGIT, and TNF) and exhaustion (e.g., PDCD1, CTLA4, LAG3, and TNFRSF9) in hepatic CD4+ and CD8 + T cells in participants with NASH or liver cirrhosis than in controls." (PMID 37735474, 2023). "In another study, the inhibition of TNF-α, IL-1β, and IL-6 overexpression by CLX in spleen tissues, suppressed splenomegaly, contributed to the development of liver cirrhosis." (PMID 35884918, 2022). "Studies have found that liver cirrhosis patients with infection have significantly higher serum endocan, CRP, TNF-α and procalcitonin levels." (PMID 35071362, 2021). "Of note, baseline expression of IFN-γ and TNF-α appeared to be higher in CD4+ and CD8+ T cells of patients with all stages of liver cirrhosis compared to healthy controls." (PMID 33574809, 2020). "Therefore, this study reports a rare case of a patient with liver cirrhosis due to AIH and UC refractory to conventional treatment and discusses the risks and benefits of using anti-tumor necrosis factor in both conditions." (PMID 39093785, 2024). "However, pretreatment inhibited the depletion of IL-10 and elevation of TNF-α and IL-6 levels, which shows its anti-inflammatory effect on TAA-induced liver cirrhosis in the rat." (PMID 36458098, 2023).
liver cirrhosis (continued). "TNFα levels are increased in liver cirrhosis even in the absence of infection, most likely owing to a continuous endotoxin influx into the portal blood." (PMID 24386183, 2013). "Based on this reasoning, the aim of the present study is to analyze the relationship of Klotho with proinflammatory cytokines (TNF-α, IL-6, and IL-8) and the lipid peroxidation products (Malondialdhyde = MDA) among alcoholics with or without liver cirrhosis, and its relationship with survival." (PMID 36009045, 2022). "In the uninfected group of liver cirrhosis, the endocan level is not correlated with other indicators, while in the infected group, the endocan level was correlated with the child-Pugh score, CRP, and TNF-α levels." (PMID 35071362, 2021).
edema (71 papers, 2009 to 2026). An abnormal accumulation of fluid beneath the skin, or in one or more cavities of the body. "IL-36 administration exacerbated pulmonary edema, inflammatory cytokine levels (IL-10,TNF-α,MPO) and histopathological injury." (PMID 42103804, 2026). "In vivo, CSE treatment significantly suppressed the expression of pro-inflammatory cytokines TNF-α and IL-6 and relieved the degree of ear edema in the TPA-induced mouse ear edema model." (PMID 37528974, 2023). "Meanwhile, 3,5-di-O-caffeoylquinic acid was reported to show an anti-inflammatory effect in the carrageenan-induced rat paw edema model through the suppression of TNF-α and IL-1β dose-dependently." (PMID 37667314, 2023). "In these lung protective studies, shionone suppressed the inflammatory response, marker genes, and pathways, such as pulmonary edema, TNF-α, IL-6, and IL-1β and ECM1/STAT5/NF-κB, which again support the anti-inflammatory properties of shionone." (PMID 38202771, 2023). "Brain edema is accompanied by IL-1β, IL-6, and TNF-α cytokines, exacerbating mitochondrial dysfunction and increasing ROS levels, leading to neuronal inflammation." (PMID 37529169, 2023). "In conjunction with the other proinflammatory cytokines, TNF-α can induce localized and systemic inflammatory events that eventually lead to tremendous lung damage, pulmonary edema, and even death." (PMID 37047115, 2023). "After CVT occurrence, microglia are activated and secrete cytokines (e.g., interleukin-1β and tumor necrosis factor-α), which result in a series of brain injuries, including blood-brain barrier disruption, brain edema, and cerebral venous infarction." (PMID 35937062, 2022). "In carrageenan-induced mouse paw edema, TNF-α promoted collateral cytotoxicity by acting as a stimulator of prostaglandin synthesis, an activator of the NF-κB signal transduction pathway, as NO formation inducer, and a stimulator of neutrophil migration." (PMID 36233038, 2022). "After treatment with the miR-124-3p agomir, the degrees of pulmonary injury (e.g. alveolar hemorrhage and interstitial edema), and the increases in IL-1β, IL-6, and TNF-α levels induced by LPS were significantly attenuated." (PMID 32391561, 2020). "Suppressing TNF-α production in serum in vivo mouse model of LPS evoked acute inflammation, reducing cotton pellet- and carrageenin-induced paw edema in rat, and so on." (PMID 32013142, 2020). "In this manner, TNF-α and IL-1 act synergistically to induce a shock-like state characterized by vascular permeability, severe pulmonary edema, hemorrhage, and fever." (PMID 32232117, 2020). "A study showed that administration of poly-ε-caprolactone microsphere polymers containing usnic acid reduced significantly IL-1β, TNF-α, and NO levels in carrageenan-induced paw edema in a rat model, results of which were similar to our findings." (PMID 32963745, 2020). "Rev-D4F inhibits LPS-induced pulmonary edema and decreases plasma levels of the pro-inflammatory mediators TNF-α and ET-1 in ALI mice." (PMID 31242908, 2019). "TNF exhibits a dual role of action in pathological conditions; specifically, TNF has been shown to contribute to the pathogenesis and development of pulmonary edema, through binding to TNF receptors and consequent initiation of the inflammatory cascade." (PMID 28611771, 2017). "Previous studies have shown that cytokines, such as TNF-α and IL-1β released from microglia under hypoxic-ischemic and inflammation conditions, are closely related to cerebral edema because they can disrupt the endothelial’s tight junction." (PMID 24916922, 2014). "Studies on the mechanisms suggest that in the early stage of SILI, smoke particles stimulate the body's inflammatory cells to release a large number of inflammatory cytokines such as IL‐1β, IL‐6, TNF‐α, resulting in increased vascular permeability and pulmonary edema." (PMID 39588955, 2024).